IL1B (interleukin 1 beta)
Diseases named in the same sentence as IL1B in open-access papers (continued):
Sharing a sentence is not in itself a finding about the gene and the disease.
Sepsis (continued). "Other studies have demonstrated that exogenous NRG1 administration attenuates oxidative stress and inflammation by inhibiting the production of reactive oxygen species IL-1β and NLRP3 inflammasome, and supports cardiac repair, sepsis, traumatic spinal cord injury." (PMID 39312480, 2024). "Sphk1 is a pro-inflammatory factor, and inhibition of Sphk1 can inhibit the activation of NLRP3 inflammasome and the release of IL-1β in macrophages and improve the survival rate and pulmonary vascular leakage of cecal ligation and puncture (CLP)-induced sepsis mice." (PMID 38482014, 2024). "The typical pro-inflammatory cytokine panel of sepsis includes TNF-α, IL-1β, IL-12, and IL-18." (PMID 37569751, 2023). "Sepsis represents a systemic response where LPS interacts with host cell receptors, generating numerous pro-inflammatory cytokines: tumor necrosis factor-alpha (TNF-α), interleukin (IL)-1β, IL-6, IL-12, and inflammatory mediators (nitric oxide (NO))." (PMID 38203627, 2023). "Exosomes derived from adipose stem cells could reduce the expression of IL-1β, TNF-α and IL-6 in macrophages during sepsis while also downregulating M1 markers (iNOS and CD86) expression." (PMID 37635258, 2023). "In our study, the plasma levels of proinflammatory cytokines IL-1β, IL-6 and TNF-α were markedly elevated in CLP group rats at 12 hours to 5 days, also demonstrating once again the successful establishment of a CLP-induced sepsis model." (PMID 37219401, 2023). "From a model of MRSA infection for 24h murine sepsis, blood samples showed the vancomycin treatment down regulated Toll-like receptor signaling pathway and IL-1β production, but not IL-6 and TNF-α production." (PMID 36844408, 2023). "Our data confirm that glutamine at 10 mM before or after stimulation cannot modulate any induction effect of either LPS or HS on relative HSP90α gene expression, monocyte HSP90α protein, and supernatant IL-1β, IL-6, IL-8, IL-10, and TNF-α concentrations of PBMCs in sepsis." (PMID 36615909, 2023). "In addition, it has been also reported that XBJ effectively reduced circulating IL-1β, IL-6, and TNF-α in CLP rats within 12 h after sepsis." (PMID 37219401, 2023). "The results of these experiments show that IL-1β stimulates TRPA1 afferent vagus nociceptors to activate an anti-inflammatory response which is protective against otherwise lethal cytokine-mediated inflammation and sepsis." (PMID 36650454, 2023). "In sepsis patients’ whole blood assays, the blockers significantly decreased supernatant concentrations of TNF and IL-6 in response to added heat-killed E. coli and S. aureus, and of IL-1β in response to S. aureus." (PMID 37869001, 2023). "We confirmed the positive correlations between the plasma levels of interleukin 1-β (IL-1β), eotaxin, interferon-α (IFN-α), tumor necrosis factor-α (TNF-α), and the reads of pathogens, and the last three remained significant in sepsis patients." (PMID 36673134, 2023). "Recent studies have revealed that hepatic macrophages can secrete distinct sets of cytokines and chemokines, including TNF-α, IL-1β, and IL-6, which are the key mediators in systemic inflammatory response syndrome (SIRS) and the generation of hepatic acute-phase proteins during sepsis." (PMID 36768433, 2023). "To explore whether SLAMF7 regulate the production of proinflammatory cytokines induced by sepsis in vivo, we determined the concentrations of TNF-α, IL-1β, and IL-6 in serum and supernatants of liver, lung, and PL." (PMID 36749634, 2023). "NLRP3 inflammasome assembly and activation can self‐cleavage to produce an active form of Caspase‐1 (pro‐Caspase‐1), promoting the release of proinflammatory cytokines including IL‐1β, IL‐18, and the alarmin high mobility group protein B1 (HMGB1), en route to inflammation of sepsis." (PMID 37206244, 2023).
Sepsis (continued). "Some studies have shown that the levels of characteristic cytokines such as TNF‐α, IL‐6, IL‐1β, IL‐1α, IL‐12, IL‐17, CXCL1, CXCL2, MCP‐1, IL‐8, CXCL10, GM‐CSF, M‐CSF, and G‐CSF in patients with septicemia are significantly higher than those in normal volunteers." (PMID 36684101, 2023). "In a murine model of sepsis by cecum ligation and puncture (CLP) and in lipopolysaccharide(LPS)‐induced cardiac fibroblasts, corticosteroid pretreatment was found to inhibit NLRP3 formation, cysteine asparaginase‐1 activation, and IL‐1β secretion." (PMID 37904696, 2023). "The results showed that the mRNA levels of IL-18, IL-1β, and procaspase-1 decreased after knockdown of USP5 in LPS-induced sepsis cell model, and overexpressed TXNIP in USP5 knockdown cells could upregulate the inflammatory factors." (PMID 37534934, 2023). "This article constructed a mouse model of sepsis and used purified mouse neutrophils for subsequent detection experiments and found that the expression of inflammatory cytokines TNF‐α, IL‐1β, and IL‐6 in activated neutrophils was significantly upregulated, consistent with previous research." (PMID 37647440, 2023). "Furthermore, the levels of IL-1β and TNF-α in lung tissues from mice with sepsis were markedly decreased by LMT-28." (PMID 36643585, 2023). "In a recent report, in mice with LPS-induced sepsis, G-Rg6 suppressed TNF-α, IL-6, and IL-1β and increased IL-10, thereby inducing the expression of miR-146a and acting as an anti-inflammatory agent in bone marrow-derived macrophages, which are known to regulate inflammatory responses." (PMID 38202632, 2023). "Furthermore, administering AM and AMBP-1 following sepsis induction in rats reduced inflammatory indices including circulating TNF-α, IL-6, and IL-1β." (PMID 37113606, 2023). "In addition, inflammatory cytokines such as interleukin-1β (IL-1β), IL-6, IL-18, tumor necrosis factor alpha (TNF-α), and interferon-gamma (IFN-γ) have been reported to play an essential role in the development of sepsis and septic shock." (PMID 37359526, 2023). "Since it is assumed IL-1β synthesis occurs in the tissue compartment, results of this study present the possibility of a hidden IL-1β tissue reservoir in sepsis that is not reflected in IL-1β blood measurements." (PMID 37928695, 2023). "Furthermore, sepsis can progress to multiple-organ dysfunction syndrome (MODS), sustained by pro-inflammatory cytokines, such as tumor necrosis factor alpha (TNFα), interleukin-1beta (IL-1β), IL-6, IL-10, and IL-12." (PMID 37298258, 2023). "In addition, in another study, we created sepsis by cecal ligation puncture method in rats, TCE significantly reduced TNF-α, IL-1β, IL-6, TOS, OSI levels, expression of caspase-3 and NF κB and increased TAS values." (PMID 37476882, 2023). "It is interesting and of important clinical significance to determine the therapeutic window for IL-1β blockade, as it is not always possible for us to inhibit IL-1β at an early stage of sepsis." (PMID 37834141, 2023). "Compared with wild‐type mice, the TLR4 knockout decreased mortality rates, improved cardiac dysfunction, and reduced expressions of IL‐1β, IL‐6, and TNF‐α in heart tissues and decreased neutrophil infiltration in cecum ligation and puncture (CLP)‐induced sepsis mice." (PMID 38455195, 2023). "As IL-1β and NF-kB were the crucial components of pyroptosis, we speculated that SJS may exerted protective role in sepsis-induced lung injury through the regulation of pyroptosis." (PMID 37062835, 2023). "A significant reduction in clinical sepsis observed in the OAC group can be attributed to the significant increase in urinary levels of sIgA and lactoferrin, and significant decrease in urinary IL-1b and salivary TGF-b." (PMID 37593258, 2023). "In septic patients, another study revealed the suppression of IL-1β release at the onset of sepsis in both survivors and non-survivors." (PMID 38140660, 2023).
Sepsis (continued). "Additionally, we demonstrated that HRS given at early onset of sepsis induction is more effective in reducing TNF-α and IL-1β than when given at later time point, though more studies are needed to validate this effect." (PMID 36435787, 2022). "However, treatment with ICOS-Fc significantly decreased IL-1β and TNF-α in WT mice and IL-1β, IL-6 and IL-10 in ICOS-/- mice indicating that ICOS-Fc substantially downmodulates the cytokine storm in sepsis." (PMID 36119089, 2022). "This may provide an energy substrate for the heart and other tissues despite an IL-1β mediated downregulation of VLDL receptors in the septic heart, thus enhancing tolerance of cardiac injury in the face of sepsis." (PMID 35911546, 2022). "FTB treatment lowered the levels of CRP, IL-6, IL-1β, and TNF-α in rats with sepsis." (PMID 36408247, 2022). "One of the cytokines showing a relevant modulation by either sepsis and PF271 was IL-1β." (PMID 35178052, 2022). "Therefore, we assessed the gene expression of pro-inflammatory cytokines IL-1β, IL-6, TNF-α, and keratinocyte chemoattractant (KC), which are increased during sepsis." (PMID 35628471, 2022). "For example, long non-coding metastasis-associated lung adenocarcinoma transcript 1 (lnc-MALAT1) and micro RNA (miR)-125a were increased in sepsis patients compared with healthy controls and positively correlated with APACHE-II score, SOFA score, serum creatinine, CRP, TNF-α, IL-1β, IL-6, and IL-8." (PMID 34991675, 2022). "Similarly, in the late phase of sepsis (seven days after the surgery), the levels of serum IFN-γ, TNFα, and IL-1β were upregulated in the CLP group compared to the sham group, while the levels of these cytokines were downregulated with cortistatin treatment." (PMID 36148090, 2022). "Furthermore, inflammatory cytokines (TNF-α, IL-1β and IL-6) in plasma and bronchoalveolar lavage fluid (BALF) were reduced, representing sepsis-induced inflammatory response was attenuated." (PMID 36030287, 2022). "NM treatment significantly reduced IL-1β mRNA expression compared to the sepsis group, whereas RM administration showed a non-significant suppression (P ​> ​0.05)." (PMID 35345558, 2022). "The data showed a marked upregulation in the expression levels of TXNIP, NLRP3, caspase-1, and IL-1β, suggesting that the NLRP3 inflammasome may contribute to liver dysfunction during sepsis." (PMID 35136484, 2022). "Interestingly, disulfiram still allows IL-1β and GSDMD processing, but abrogates pore formation, thus preventing IL-1β release and pyroptosis in LPS-induced sepsis." (PMID 36131917, 2022). "Finally, the relationships involving IL-1β, C3, succinate, and inosine were investigated in two in vivo models, namely: mice infected with V. alginolyticus, E. tarda or E. coli, gram-negative bacterial pathogens associated with sepsis, or the vertebrate tilapia exposed to E. tarda." (PMID 36026499, 2022). "However, HRS given as early as 1 h after LPS-induced sepsis was more effective in decreasing TNF-α and IL-1β expression levels and increasing IL-10 levels compared to other time intervals (p < 0.05)." (PMID 36435787, 2022). "Due to our initial observations of the ability of AZ106 to prevent endothelial dysfunction in response to IL‐1β, we hypothesized that AZ106 might prevent endothelial dysfunction during murine polymicrobial sepsis." (PMID 35668576, 2022). "Interestingly, expression of inflammatory mediators IL-1β, IL-6, TNFα, iNOS, and COX2 decreased in the presence of a mitoNEET inhibitor, NL-1, or upon expression of mitoNEET shRNA, even in the LPS-induced sepsis model." (PMID 35136051, 2022). "In diseases satisfactorily treated with anti-IL-1 therapy, such as sepsis or autoinflammatory syndromes, the blood concentrations of IL-1β are very low and usually not detected." (PMID 35663992, 2022).
Sepsis (continued). "Conversely, several of these cytokines (IL‐1β, IL‐6, TNF‐α, CXCL1) were significantly elevated in AZ106‐treated mice compared to those subjected to CS alone, indicating a potential role for P2X7R in the modulation of the inflammatory response during sepsis." (PMID 35668576, 2022). "Furthermore, sepsis led to a significant increase in plasma and myocardial levels of pro-inflammatory factors, such as TNF-α and IL-1β, compared with those in the control group, whereas the EA pre-treatment reduced inflammation compared with the LPS group." (PMID 36160853, 2022). "The levels of IL-6, TNF-α, IL-1β, CD4+, and CD8+ in the three groups of patients were compared to analyze the correlation of blood glucose levels with inflammatory response and immune indicators in patients with sepsis." (PMID 35664433, 2022). "Moreover, the secretion of PSM-mec toxins increased cytokine expression (IL-1β, TNF-α and the mouse IL-8 homologue CXCL1), leading to elevated sepsis severity in a murine model of sepsis." (PMID 35055041, 2022). "Similar results were shown in models of acute lung injury after sepsis (decreased TNF-α, IL-1β, and IL-6 secretion) and paraformaldehyde injury (decreased cell death, MyeloPeroxidase activity, parenchymal vascular permeability, TNF-α and IL-6 secretion, and increased IL-10 secretion)." (PMID 35874678, 2022). "We report here that experimental sepsis led to an overactivation of the NLRP3 complex and consequent activation of its downstream mediator caspase-1, which were significantly reduced by treatment with ICOS-Fc, thus leading to reduced systemic release of IL-1β." (PMID 36119089, 2022). "Additionally, 6-gingerol (20 mg/kg, orally) significantly improved sepsis development in CLP mice, as observed by a decrease in serum IL-1β." (PMID 36588685, 2022). "Also, high expression of IL-1β and lncRNA CHRF has been detected in mice with sepsis while knockdown of lncRNA CHRF reduces inflammatory reaction." (PMID 35711847, 2022). "The present study showed that TXNIP knockdown significantly inhibited hippocampal microglia activation in the sepsis mice, while the NLRP3 and cleaved caspase-1 protein expression levels and the inflammatory factors, IL-1β and IL-18, were significantly reduced in the hippocampus." (PMID 35571246, 2022). "The co-existence of LPS and bacterial DNA in the serum of sepsis mice (CLP and LPS models) may enhance systemic inflammation through macrophage M1 polarization (iNOS and IL-1β expression) and NFκB upregulation." (PMID 35163830, 2022). "In addition, MSCs were able to reduce the levels of pro-inflammatory cytokines such as IL-1β, IL-6 and TNF-α and elevate the levels of anti-inflammatory cytokines such as IL-10 and TGF-β in the circulation of aged sepsis model rats." (PMID 35197984, 2022). "To explore whether AC-YVAD-CMK could affect the NLRP1 inflammasome signaling pathway to improve sepsis-induced acute kidney injury, we measured the expression levels of Caspas-1, NLRP-1, IL-1β, and IL-18 by Western blotting." (PMID 34222479, 2021). "The prediction of CFIG targets showed that the CFIG of XBJI could affect sepsis synergistically through genes such as TAK1, TNF-α, IL-1β, and MEK1 in the pathways of MAPK, NF-κB, PI3K-AKT, Toll-like receptor, and tumor necrosis factor signaling." (PMID 34938184, 2021). "Although our data suggest that the NLRP3 pathway primarily activates IL‐1β in sepsis, further studies are needed to elucidate the role of the non‐canonical and alternative IL‐1β‐activating pathway in sepsis." (PMID 34472725, 2021). "IL-6, IL-12, IL-1β and TNF-α are important inflammatory cytokines in sepsis." (PMID 33995024, 2021). "The addition of LPS and IL-1β, which are known to be important factors that contribute to sepsis, did not significantly affect DC generation from HSPCs." (PMID 34566996, 2021).
Sepsis (continued). "Quercetin was reported to protect mice from LPS-induced sepsis by inhibiting TNF-α and IL-1β expressions, NF-κB activation, and apoptosis and proposed to prevent myocardial dysfunction through the TLR4/NF-κB signaling pathway during sepsis." (PMID 34938184, 2021). "Besides, the injection of miR-378a-3p antagomir hindered the inflammatory response augment induced by sepsis, presenting as the downregulation in TNF-α, IL-1β, IL-6 (P < 0.05)." (PMID 34565302, 2021). "The early phase of sepsis is characterized by excessive inflammation with the manifestation of systemically boosted production of pro-inflammatory cytokines, including TNF-α, IL-6 and IL-1β." (PMID 33842398, 2021). "The results showed that AC-YVAD-CMK treatment significantly reduced the expression levels of Caspas-1, NLRP-1, IL-1β, and IL-18 compared with those of the CLP group, confirming that AC-YVAD-CMK could reduce pyroptosis and sepsis-induced acute kidney injury." (PMID 34222479, 2021). "In the early stage of sepsis, macrophages promote host defense by eliminating invading pathogens or damaged tissues and releasing abundant amounts of proinflammatory cytokines, such as TNF-α, IL-1β, and IL-6." (PMID 34220338, 2021). "Moreover, the broad-spectrum caspase inhibitor VX-166 exhibited strong anti-apoptotic and anti-inflammatory effects by inhibiting IL-1β and IL-18 release in the CLP rat model and showed significant therapeutic effects against sepsis." (PMID 34305952, 2021). "Using CLP, a clinically relevant murine model of gram-negative polymicrobial sepsis, we observed that FeTPPS treatment markedly inhibited caspase-11-dependent release of IL-1α and IL-1β, but did not affect the secretion of TNF or IL-6." (PMID 33854044, 2021). "Although we observed a relatively high activity of caspase-1 in sham mice, sepsis did not increase it further, and there was no significant increase in IL-1β in the BM." (PMID 34367170, 2021). "According to previous studies, increased levels of circulating cytokines like TNF‐α, IL‐1β and IFN‐γ are typical characteristics of sepsis, which may induce endothelium dysfunction, pathological procoagulant state and exacerbate liver injury as well." (PMID 33982381, 2021). "Intraperitoneal injection of lipopolysaccharide induces sepsis, and the activation of the NLRP3 inflammasome plays a crucial role in vivo, accompanied by the production of IL-1β and the occurrence of inflammation." (PMID 34721038, 2021). "Regarding the intermediate monocytes, such an exaggerated elevation has been shown in severely injured patients 48 h post-trauma and under inflammatory conditions such as sepsis or bacterial and viral infections, paralleled by sequestration of high amounts of TNF-α, IL-1β, and IL-6." (PMID 34575249, 2021). "In addition, serum cytokine levels of IL-1β, IL-6, IL-8, IL-10, IL-12, IL-17A, IL-18, IFN-γ, TNF-α, and calprotectin were found to be elevated in sepsis." (PMID 34654467, 2021). "Many of the measured cytokines/chemokines/immune-modulators were proven to be pathogenic in sepsis and septic shock; however, single targeting of cytokines did not ameliorate sepsis in many trials using anti-TNF, anti-IL-1β, and other cytokines." (PMID 34659208, 2021). "The levels of cytokines IL-1β, IL-6, IL-8, MCP-1, and IL-10, and of plasminogen activator inhibitor 1 (PAI-1), were reported to be increased over the acute phase and that IL-6, IL-8, MCP-1, and IL-10 formed a cytokine network in the acute phase of sepsis." (PMID 34654467, 2021). "During sepsis, LPS/LTA can activate the MAPK signaling pathway, and further accelerate the production of proinflammatory cytokines, such as IL-1β, IL-6, and TNF-α, which form the cytokine cascade, and eventually leads to cell apoptosis and multiple organ dysfunction." (PMID 34483941, 2021).